GPAT3 (glycerol-3-phosphate acyltransferase 3)
Description:
Converts glycerol-3-phosphate to 1-acyl-sn-glycerol-3-phosphate (lysophosphatidic acid or LPA) by incorporating an acyl moiety at the sn-1 position of the glycerol backbone. Also converts LPA into 1,2-diacyl-sn-glycerol-3-phosphate (phosphatidic acid or PA) by incorporating an acyl moiety at the sn-2 position of the glycerol backbone. Protects cells against lipotoxicity.
Synonyms: AGPAT 10; LPAAT-theta; AGPAT9; MAG1; HMFN0839; MGC11324; AGPAT10; AGPAT8
Tractability: Antibody: UniProt predicts a signal peptide or a membrane-spanning region. PROTAC: ubiquitination databases record sites on it.
Target class: Enzyme; Transferase
Gene: Protein-coding gene on chromosome 4 (83,535,619 to 83,605,875, forward strand). Ensembl gene ENSG00000138678.
Subcellular location: Endoplasmic reticulum membrane
Pathways (Reactome):
Metabolism: Synthesis of PA
Gene Ontology:
Molecular function: 1-acylglycerol-3-phosphate O-acyltransferase activity; glycerol-3-phosphate O-acyltransferase activity; acyltransferase activity; lysophosphatidic acid acyltransferase activity
Biological process: regulation of TOR signaling; triglyceride biosynthetic process; phosphatidic acid biosynthetic process; CDP-diacylglycerol biosynthetic process; glycerol-3-phosphate metabolic process; phospholipid biosynthetic process
Cellular component: endoplasmic reticulum; endoplasmic reticulum membrane
Genetic constraint (gnomAD): Loss-of-function variants: 50 observed, 54.91 expected, observed/expected ratio (o/e) 0.91, 90% interval 0.73 to 1.15. The upper end of that interval is the gene's LOEUF score, 1.15, which puts it in group 5 of 6, group 1 being the genes least tolerant of losing a copy. Missense variants: 479 observed, 511.76 expected, observed/expected ratio (o/e) 0.94, 90% interval 0.87 to 1.01. Synonymous variants: 182 observed, 186.17 expected, observed/expected ratio (o/e) 0.98, 90% interval 0.87 to 1.11.
Homologues: Orthologues: chimpanzee GPAT3 (99% identical), macaque GPAT3 (99% identical), dog GPAT3 (98% identical), rabbit GPAT3 (97% identical), pig GPAT3 (94% identical), mouse Gpat3 (94% identical), guinea pig GPAT3 (92% identical), tropical clawed frog gpat3 (77% identical). Paralogues in human: GPAT4 (69% identical), LPCAT2 (19% identical), LPCAT4 (18% identical), LPCAT1 (16% identical).
Diseases named in the same sentence as GPAT3 in open-access papers:
GPAT3 is named in the same sentence as 51 diseases in open-access papers, as found by Europe PMC text mining. Sharing a sentence is not in itself a finding about the gene and the disease. The quoted sentences say what the papers report.
Obesity (6 papers, 2019 to 2025). Accumulation of substantial excess body fat. "The knockout of the GPAT3 gene altered energy balance in diet-induced obesity in mice, indicating that the GPAT3 gene plays a role in regulating energy and lipid homeostasis." (PMID 35847642, 2022). "Microsomal isoform GPAT3 deficiency using knockout mice shows that GPAT3 accounts for predominant GPAT activity in WAT, which is closely related to obesity." (PMID 30813330, 2019).
Insulin resistance (4 papers, 2022 to 2025). Increased resistance towards insulin, that is, diminished effectiveness of insulin in reducing blood glucose levels. "Mice with severe congenital generalised lipodystrophies exhibit insulin resistance and hepatic steatosis when GPAT3 is deficient." (PMID 36950134, 2023). "Moreover, loss of function of GPAT3 alleviates insulin resistance and hepatic steatosis in seipin-/-mice (a mouse model of severe congenital generalized lipodystrophy)." (PMID 36964139, 2023). "The promoter polymorphisms of the GPAT3 were associated with intramuscular fat content in Laiwu pigs, and the knockout of GPAT3 was related to insulin resistance and fatty liver in a mouse model of severe congenital generalized lipodystrophy." (PMID 35847642, 2022).
Hepatic steatosis (3 papers, 2020 to 2025). Steatosis is a term used to denote lipid accumulation within hepatocytes. "Whilst this manuscript was in revision, Gao and colleagues reported that additional disruption of GPAT3 can improve insulin tolerance and reduce hepatic steatosis in seipin-null mice." (PMID 32094408, 2020).
hepatocellular carcinoma (2 papers, 2024 to 2025). A malignant tumor that arises from hepatocytes. "Here, we study the regulatory mechanism of GPAT3 gene expression in human hepatoma cells suffering from ER stress." (PMID 41392190, 2025). "In the current article, we characterize the mechanism of GPAT3 expression regulation in HepG2 human hepatoma cells suffering from ER stress." (PMID 41392190, 2025). "Recently, it was found that in hepatocellular carcinoma (HCC) cells, GPAT3 upregulation reprograms lipid metabolism, and contributes to acquired resistance to sorafenib, the standard treatment for advanced HCC18." (PMID 41392190, 2025).
inflammatory liver disease (2 papers, 2023 to 2025). "Overall, this study highlights the role of GPAT3 in inflammatory activation of KCs and could thus be a potential therapeutic target for the treatment of inflammation-related liver disease." (PMID 36964139, 2023). "Our discovery suggests that targeting GPAT3 may be an effective therapeutic strategy for regulating the inflammatory response of KCs and improving inflammatory liver disease." (PMID 36964139, 2023).
steatosis (2 papers, 2018 to 2023). Increased lipid within the cytoplasm of cells. "More specifically, perturbation in endoplasmic reticulum and vesicles through the genes MUL1, TMEM135, OSBPL9, SCD1, SREBP-1C, GPAT3 can lead to steatosis." (PMID 30279702, 2018).
Anxiety (1 paper, 2021). Intense feelings of nervousness, tension, or panic often arise in response to interpersonal stresses. "Interestingly, among the anxiety- and depression-related DEGs, we found the upregulation of Bcl3, C3, Gpat3, and Tnf in the AMY as well as the increased expression of Crhr2, Nant, Sar1a, and Tgif1 and the decreased expression of Ier2, Il12a, Nrep, and Tnfrsf25 in the ACC." (PMID 33898422, 2021).
brain cancer (1 paper, 2024). A primary or metastatic malignant neoplasm affecting the brain. "GPAT3 expression in CRC cells was lower than that in brain cancer, esophageal cancer, gastric cancer, and liver cancer cells (RNAseq.log2 = 2.93)." (PMID 38344398, 2024).
Cirrhosis (1 paper, 2023). A chronic disorder of the liver in which liver tissue becomes scarred and is partially replaced by regenerative nodules and fibrotic tissue resulting in loss of liver function. "Our results showed that several crucial drivers, including regulators that are potentially associated with the progression of cirrhosis, such as SLC40A1, DAB2, FOLR2, GPAT3, and CDA, were upregulated during fibrosis." (PMID 36845083, 2023).
colorectal cancer (1 paper, 2018). A primary or metastatic malignant neoplasm that affects the colon or rectum. "For GPAT3-TRIP13 gene pair, both up-regulation of TRIP13 and down-regulation of GPAT3 contribute to the reversal REO in colorectal cancer samples." (PMID 29378509, 2018).
diabetes (1 paper, 2014). "Inhibitors of GPAT3, possibly mediating the prevention of adipocyte hypertrophy, might be used in the treatment of diabetes." (PMID 25415055, 2014).
hepatitis B (1 paper, 2024). "In addition, FOSB is reported to be related to hepatitis C, while RNF43 and GPAT3 are related to hepatitis B." (PMID 38965537, 2024). "We also detected the expression of FOSB, GPAT3, RGCC, and RNF43 in the blood of patients with hepatitis B, hepatitis C and AIH." (PMID 38965537, 2024). "We also examined FOSB, GPAT3, RGCC, and RNF43 expression in patients with hepatitis B, hepatitis C, and AIH." (PMID 38965537, 2024).
hyperlipidemia (1 paper, 2025). "The expression of genes related to the production and storage of fat inside the liver (SREBP-1c, ACC, FAS, GPAT3, SCD1, and FSP27) were all significantly (P < 0.05) upregulated in the liver of hyperlipidemia group." (PMID 41144456, 2025).
leprosy (1 paper, 2021). Leprosy is a chronic infectious disease affecting primarily the skin and peripheral nervous system. "Our finding indicates that GPAT3 also plays an important role in the intracellular survival of M. leprae, suggesting that GPAT3 may become a novel target for leprosy treatment." (PMID 33770127, 2021).
lipid metabolic disorder (1 paper, 2023). "LPA is a key link between the elevated GPAT3 levels and a KC lipid metabolic disorder that drives the development of inflammation in KCs." (PMID 36964139, 2023).
rectal carcinoma (1 paper, 2024). A malignant epithelial neoplasm that arises from the rectum and invades through the muscularis mucosa into the submucosa. "In expression analyses of TCGA tissue samples, GPAT3 mRNA levels were notably lower in colon and rectal carcinoma samples than in normal samples." (PMID 38344398, 2024).
renal carcinoma (1 paper, 2020). A carcinoma arising from the epithelium of the renal parenchyma or the renal pelvis. "Data from TCGA suggested that GPAT1 could be a favorable prognostic marker in renal cancer, while GPAT3 is a putative biomarker of good prognosis in renal cancer in contrast to urothelial cancer." (PMID 33194695, 2020).
infection (12 papers, 2015 to 2025). The state of being infected such as from the introduction of a foreign agent such as serum, vaccine, antigenic substance or organism. "More than 80% of THP-1 cells were fluorescent at 3 h post-infection and the levels of such cells were similar between wild-type and GPAT3 KO cells until 6 h." (PMID 33770127, 2021). "The increase in GPAT3 mRNA was apparent as early as 6 h after M. leprae infection and increased up to 48 h post-infection." (PMID 33770127, 2021). "Stimulation of macrophages via toll-like receptors shifts metabolism to lipid storage in preparation to fight infection with concomitant increase of a set of lead enzymes, among them GPAT3." (PMID 32675052, 2020). "After infection, M. leprae localized in lipid droplets in wild-type cells, whereas the number of both intracellular M. leprae and lipid droplets was clearly reduced in GPAT3 KO cells." (PMID 33770127, 2021). "Intriguingly, the expression of GPAT3 that encodes an enzyme that also converts LPA to PA, remained unchanged at 6 h but are subsequently downregulated as the infection proceeded, displaying an opposing expression pattern from LCLAT1 during late infection." (PMID 28993767, 2017).
tumor (7 papers, 2014 to 2025). "In conclusion, these findings revealed the role of GPAT3‐associated LD accumulation, which conferred a malignant phenotype (chemoresistance) and regulated the tumor microenvironment of CRC." (PMID 38344398, 2024). "However, according to GEPIA, higher expression of AGPAT10/AGPAT9/GPAT3 in glioblastoma tumor tissue is associated with a worse prognosis." (PMID 37046844, 2023). "In this study, FABP4, PPARGC1A, AGPAT4, ALDH1A1, and GPAT3 were identified as downregulated tumor suppressor genes in TC, whereas TGFA was recognized as an oncogene." (PMID 40119647, 2025). "It showed that Gpat3 (mouse) significantly promoted tumor metastasis under Oxa treatment, as compared with L‐Vector group." (PMID 38344398, 2024). "We identified a previously undiscovered link between GPAT3‐mediated LD accumulation and tumor resistance to Oxa in CRC." (PMID 38344398, 2024). "In particular, GPAT3‐mediated LD accumulation inhibited immunogenic cell death of tumor, and thus facilitated CD8+ T‐cell exhaustion and malignant progression in mouse xenografts and hepatic‐metastasis tumors in CRC patients." (PMID 38344398, 2024). "As the bioinformatical analyses suggested that GPAT3 played an essential role in modulating cell immunological function, we further assessed the changes of tumor immune infiltration by abdominal metastases models." (PMID 38344398, 2024). "To evaluate the effect of GPAT3‐induced LD accumulation on tumor aggressiveness under chemotherapy in vivo, we subcutaneously vaccinated the nude mice with L‐Vector or L‐GPAT3 cells, generating three groups: L‐Vector cells + Vehicle, L‐Vector cells + Oxa, and L‐GPAT3 cells + Oxa." (PMID 38344398, 2024). "Second, GPAT3‐mediated LD production might be essential for the attenuation of drug‐induced tumor ICD and CD8+ T‐cell killing effects." (PMID 38344398, 2024). "Targeting GPAT3 mediated LD accumulation pathway might be a novel avenue to reverse chemoresistance and remodel tumor microenvironment." (PMID 38344398, 2024). "We identified a previously undiscovered link between GPAT3‐mediated LD accumulation and tumor resistance to chemotherapy in CRC, with applying HPLC–MS, molecular dynamics simulation, lipidomics, immunoprecipitation, immunofluorescence, flow cytometry, and so on." (PMID 38344398, 2024). "This suggesting that high GPAT3/LD production tumor exhibited an immune suppression microenvironment, which might facilitate tumor malignant progression." (PMID 38344398, 2024). "We showed both in vitro and in vivo that GPAT3 played an important role in LD accumulation, which conferred CRC chemoresistance by interfering tumor ICD." (PMID 38344398, 2024). "In this study, we found that GPAT3 conferred CRC chemoresistance and inhibited tumor ICD through GPAT3‐supported LD accumulation." (PMID 38344398, 2024). "Analysis of the GEO database showed a 2-fold elevation in GPAT3 expression in xenografted tumor tissues with SR, but not in oxaliplatin and levantinib resistant HCC cells." (PMID 38948063, 2024). "In the absence of sorafenib treatment, the growth rate and tumor weight of SR xenografts remained unchanged following GPAT3 knockdown." (PMID 38948063, 2024).
cancer (3 papers, 2018 to 2025). A tumor composed of atypical neoplastic, often pleomorphic cells that invade other tissues. "Scd, Scd2, Dgat2, Fads2, Lpin1, Gpat3, Acaa2, Lpcat3, Pcyt2 and Pla2g4a have been reported to be closely associated with cancer." (PMID 35122680, 2022).
gastrointestinal disorders (1 paper, 2024). "In the present study, Etnppl gene was found to be positively correlated with Pgs1 and Gpat3 protein in T2DM -induced gastroenteropathy, with elevated levels of Pgs1 and Gpat3 protein expression." (PMID 39211388, 2024).
GPAT3 also shares sentences with these, for which no sentence is quoted: cyst (23 papers); toxoplasmosis (6); generalized lipodystrophy (2); metabolic dysfunction-associated steatohepatitis (2); AIDS (1); autoimmune disease (1); breast carcinoma (1); breast tumors (1); Cerebellar atrophy (1); chronic hepatitis B (1); Cognitive impairment (1); depression (1); esophageal cancer (1); gastric cancer (1); Hepatitis (1); hepatitis C (1); inflammation (1); latent infection (1); lipodystrophy (1); liver (1); liver cancer (1); lupus (1); ocular toxoplasmosis (1); parasitemia (1); Pleural effusion (1); rheumatoid arthritis (1); schizophrenia (1); Sepsis (1); small cell carcinoma (1); viral infections (1).